TNF (tumor necrosis factor)
Diseases named in the same sentence as TNF in open-access papers (continued):
Sharing a sentence is not in itself a finding about the gene and the disease.
infection (continued). "Here, we uncover that the ovarian tumor deubiquitinating enzyme 7b (OTUD7b) prevents TNF-induced apoptosis of DCs in infection, resulting in efficient priming of pathogen-specific CD8+ T cells." (PMID 37516734, 2023). "When bacteria and other pathogens enter our body, macrophages secrete inflammatory mediators including NO, PGE2, and proinflammatory cytokines (IL-6, IL-1β, and TNF-α) that attract immune cells to the site of infection and activate cells to eliminate them." (PMID 37513335, 2023). "Therapeutic blockade of TNF in the context of autoinflammatory diseases results in greatly increased rates of infection." (PMID 37279255, 2023). "Infection with these bacteria induced solid inflammatory responses and a substantial increase in the inflammatory cytokine release of TNF‐α, IL‐6, IL‐1β, and IL‐18 in macrophages derived from March5fl/fl mice." (PMID 37575012, 2023). "Infection with ply+lytA+ strain A66 induced detectable IFNγ, IL-6, TNFα, RANTES, IL-1α and IL-1β in the lungs of inoculated mice, and all but IL-1α in the bloodstream." (PMID 36897919, 2023). "Upregulation of CD1d recognized by γδ T cells to activate autoimmune CD8+ T cells requires both an active infection and the presence of TNF-α signaling." (PMID 37175422, 2023). "In the initial stage of infection, groups C and D had lower levels of the proinflammatory cytokines IL-6, TNF-α, and IFN-γ and higher levels of anti-inflammatory cytokine IL-10 than the other groups." (PMID 37051240, 2023). "This allowed us to examine secretion of TNF-α at an early time point after infection and with single cell resolution." (PMID 36852737, 2023). "A pro-inflammatory environment is also observed post-infection or after TNF-α administration in animal models, and presumably favors the proliferation of TET2-mutant stem cells, triggering a higher proportion of circulating TET2-mutant immune cells." (PMID 36835370, 2023). "It has been previously reported that LPS+IFN-γ primed Xiap−/− macrophages express reduced levels of IL-6 and TNFα upon infection with Listeria monocytogenes." (PMID 37347786, 2023). "At the beginning of an infection, neutrophils are recruited similarly as in the event of an acute infection, but in the process of biofilm maturation, pro-inflammatory cytokines, e.g., interleukins and TNF, are produced." (PMID 37760822, 2023). "There are evidences that IL-10-dependent regulation of TNF, IL-6, and IL-1 reduces the inflammatory response, also reducing the probability of PB induced by infection and inflammation." (PMID 37340384, 2023). "During the early phase of UPEC infection, the host cells release different factors, such as cytokines and chemokines (IL-1β, IL-6, IL-8 and TNF-α) and hormones (norepinephrine, estradiol), to fight off the infection." (PMID 37759520, 2023). "In neutrophils, LCN2 secretion is highly stimulated by inflammation and infection activation, and LPS and TNF‐α are two potent inducers of LCN2 production." (PMID 37060578, 2023). "In the present study, infection with F. necrophorum significantly increased the expression of TNF-α, IL-8, and IL-1β, and these inflammatory cytokines further mediated the inflammatory response of the cow intertoe skin." (PMID 37153149, 2023). "The results showed that mRNA expressions of CXCL8 and TNF in hPBDMs infected with both fungi were significantly induced beginning from 4 h post-infection and the inductions were time-dependent." (PMID 37695039, 2023). "Infection with bacteria activates pro-inflammatory gene programs, such as expressing the IL-1β, IL-6, and tumor necrosis factor genes through transcription factors." (PMID 37958634, 2023). "IL-6 is considered one of the most important cytokines during an infection, along with IL-1 and TNF-α." (PMID 36707891, 2023). "The secretion of TNF-α, IL-1β, and IL-6 can be up-regulated in response to infection with B. bronchiseptica, as these cytokines play a role in the immune response to the bacteria." (PMID 38066337, 2023).
infection (continued). "As in the experiments above, our data shows that cells infected with exosome-free L. braziliensis produced significantly less IL-1β, TNF, IL-10 and IL-6 upon infection." (PMID 37841240, 2023). "We found that soluble TNF is involved in the migration of CD4 + cells during infection and the synthesis of chemokines." (PMID 38036985, 2023). "Next, we examined the transcription level of proIL-1β and TNF-α in the macrophages at an MOI of 2 or 10 for 6 h after infection with M. ulcerans." (PMID 37910490, 2023). "These cells rapidly respond to infections by secreting inflammatory cytokines [IL-6, IL-12, tumour necrosis factor-alpha (TNF-α) and IL-1β] to repair damaged tissue." (PMID 36601859, 2023). "The expression of some inflammatory molecules (IL-1β, IL-6, IL-12, and TNFα) significantly decreased in the siIRF5-treated group, which differed from that in miR-146b deficiency following CFT073 infection." (PMID 37909731, 2023). "At 8h post-infection, there was a modest but statistically significant decrease in TNF secretion from Psme1/2-/- BMDMs infected with L. pneumophila ΔΔ (plegC4) (P = 0.049) but no other PA28αβ-mediated differences were observed." (PMID 37347796, 2023). "Subsequently, we determined the expression of TNF-α and IL-1β, the representative inflammatory factors in the small intestine during the early stage of infection by qPCR, and the results were consistent with the pathological results of the sections." (PMID 37585413, 2023). "High levels of TNFα are detected in CD patients and secretion of TNFα occurs post-infection of macrophages by AIEC." (PMID 37311220, 2023). "TNF-α, IL-6, and IL-1β are primary cytokines generated by activated macrophages during initial inflammatory responses of host defense and infection, consistent with previous reports." (PMID 38015971, 2023). "Overall, in this study, we found that Del2R infection induces high levels of IL-1β and TNF-α in vitro and in vivo, and the MGF300-2R plays a critical role in inhibiting the production of inflammatory cytokines." (PMID 37566637, 2023). "Several plasma cytokines had an increased fold change following infection with the most robust increases observed with CXCl10, TNFα, IL-10, and IL-1RA, corroborating previously published data." (PMID 37857783, 2023). "The protection observed in Zi-treated mice was associated with a lower inflammatory score, reduced dendritic cell-producing tumor necrosis factor (TNF), and increased neutrophil-producing interleukin (IL)-10 in the lungs three days after infection (dpi)." (PMID 37896826, 2023). "TNF α is a proinflammatory cytokine produced by macrophages in response to inflammation, infection, or tissue damage." (PMID 36865739, 2023). "Because of the crucial role of TNF-α in inflammation, infection and immunity, the role of TNF-α and its receptors has been vigorously investigated." (PMID 36985352, 2023). "The percentages of IFN‐γ+ cells that were also expressing IL‐2 and/or TNF were the same before and at day 5, and day 35 following re‐infection." (PMID 37490492, 2023). "Infection with Mon601 induced production of TNF-α and IL-1β RNA, and the EHI0578Y05 strain also stimulated expression of TNF-α RNA." (PMID 37515098, 2023). "TNF-α is a proinflammatory cytokine that facilitates endothelial activation and the recruitment of leukocytes to infection sites." (PMID 38006030, 2023). "In vivo data indicated that IFNγ and TNFα were involved in osteoclastogenesis and bone resorption during infection." (PMID 37153579, 2023). "Infection of TNF-primed Ripk3-/-Casp8DA BMDMs resulted in substantial increase in cell death, as measured by PI uptake, relative to unprimed Ripk3-/-Casp8DA BMDMs." (PMID 37279255, 2023). "Next, to examine the role of G3BP1, a key SG component in apoptosis, we transfected G3BP1-specific siRNA into HeLa cells following CVB3-GFP infection or TNF-α/CHX treatment." (PMID 36864501, 2023).
infection (continued). "Anti-TNF drugs should also be questioned in specific infection types and repetitive infection patterns that suggest the possibility of immunosuppression in the EDs." (PMID 37274971, 2022). "Pretreatment with TNFα prior to infection at a high multiplicity of infection (MOI = 3.0) substantially reduced the accumulation of HCMV proteins throughout infection." (PMID 35834576, 2022). "In order to evaluate the influences of CRKP colonization and translocated infection on inflammatory factor expression, interleukin-1β (IL-1β), tumor necrosis factor alpha (TNF-α), IL-6, and IL-10 concentrations were analyzed." (PMID 36445086, 2022). "Endothelial cells can be activated by vascular endothelial growth factor (VEGF), also known as VEGF-A, TNF-α, and by mediators produced by the Plasmodium parasite during infection." (PMID 35677654, 2022). "The polyfunctional CD4 T cells producing multiple proinflammatory cytokines (IFN-γ, TNF-α, and IL-2) which one correlate with protection from infection and disease." (PMID 35638072, 2022). "In humans, children exposed to early-life antibiotics have been found to exhibit lower infection-induced cytokines, including interleukin 1β, interferon α, interferon γ, tumor necrosis factor α, and IP10 protein." (PMID 35432330, 2022). "At a more recent time, TNF-α has been identified as part of the innate immune system response to infection, trauma, and ischemia–reperfusion." (PMID 36091399, 2022). "Influenza virus infection induced the release of inflammatory responses, with IL-6 and TNF-α levels in nasal irrigation fluid peaking early in the infection (day 2), and correlating directly with viral titers, temperature, mucus production, and symptom scores." (PMID 36034844, 2022). "DDIT4 knockout markedly suppressed E. coli-induced pro-inflammatory IL-1β and TNF-α expression, as well as infection-induced NF-κB p65 phosphorylation and nuclear translocation." (PMID 34985734, 2022). "While CD8+ T cells contribute to control of bacterial growth via IFN-γ and TNF-α early in the infection, CD4+ T cells have been shown to be more important in the later stages of infection, especially in cases of reinfection." (PMID 35498397, 2022). "The principal cytokines released by the host on infection include pro-inflammatory cytokines such as interleukin (IL)-1, IL-6, and tumor necrosis factor (TNF)." (PMID 35698506, 2022). "The inflammation of mediators, such as NO, TNF-α, IL-1β, and IL-6, among others, is activated due to the presence of tissue damage or infection; therefore, the concentrations of these mediators increase in the damaged areas." (PMID 35890070, 2022). "polymorphum and S. gordonii promoted hGECs to secrete the proinflammatory factors TNF-α and IL-6 at 24 h of infection, while inhibiting the secretion of the anti-inflammatory factor TGF-β1." (PMID 35573793, 2022). "TNF-α, IL-6 and NO production was analyzed from supernatants of each infection at all infection times." (PMID 35531337, 2022). "C. sinensis infection caused diminished Th1 cytokines (IL-1β, IL-2, IL-12p70, IFN-γ and TNF-α), Th2 cytokine (IL-4), as well as Th17 cytokine (IL-17A) in sera, which showed decreasing trend by infection intensity." (PMID 36083861, 2022). "A dose dependent production of pro-inflammatory (TNF, IL-6 and IL-12p40) and anti-inflammatory (IL-10) cytokines in BM-DCs supernatants was observed after infection with all leptospires." (PMID 35812397, 2022). "Histamine, TNF-α, and tryptase released in orchiectomized mice at 30 min showed a weak stain, as compared with sham mice, which increased throughout the infection time." (PMID 35456073, 2022). "MDM1 and MDM2 subpopulations express genes enriched for INFɣ responses, TNF signaling via NF-κB, and inflammatory responses, suggesting the immune stimulating function of these cells during infection." (PMID 36420267, 2022).
infection (continued). "As age is a risk factor for infection, 17% of patients over 60 years of age receiving vedolizumab have been found to develop an infection in the first year of treatment and 20% of patients receiving anti-TNF-α for IBD." (PMID 35323234, 2022). "As an example, we observed a predominant modulation of IL-6 via TLRs after infection with M. circinelloides, and TNF-α production via CTLs after infection with R. delemar." (PMID 36311802, 2022). "Infection leads to release of various pro-inflammatory cytokines, such as interleukin (IL)-1α, IL-6, tumor necrosis factor-alpha (TNFα), and interferon gamma (IFN-γ)." (PMID 35874547, 2022). "In part, this is attributed to the capacity of low physiological levels of estrogen to stimulate the production of the acute inflammatory cytokines interleukin-6 (IL-6) and tumor necrosis factor (TNF), which are active in infection control." (PMID 36273184, 2022). "Soluble tumor necrosis factor receptors 1 and 2 (sTNF-R1 and sTNF-R2) are reported to protect against excessive TNF-α, a primary mediator of systemic responses to infection." (PMID 35200250, 2022). "On the other hand, TLR4 inhibition promoted a significant reduction of IL-1β after infection with L. corymbifera and M. circinelloides and TNF-α in response to M. circinelloides." (PMID 36311802, 2022). "Our findings of reduced activated T cell numbers in TNFR1/2-/- mice suggest a role of TNF-α signaling in promoting T cell activation following infection, since both TNFR1 and TNFR2 were essential for T cell activation and IFN-γ production in vivo." (PMID 35479068, 2022). "No significant change of bacterial load was observed over time and infection triggered the production of TNF‐α, mirroring findings in other in vitro and in vivo studies." (PMID 34570407, 2022). "TNF-α is an inflammatory cytokine produced by macrophages/monocytes during acute inflammation and is essential in fighting cancer and infection." (PMID 35624855, 2022). "To gain more insight into the mechanism underlying the TLR2-mediated production of TNF-α and IL-1β in monocytes, we pharmacologically targeted key molecules of signaling downstream of TLR2 prior to infection." (PMID 36240261, 2022). "The variables that best predicted the infection status were the TNF-alpha and IL-2 value from the second sampling, leading to AUC values of 0.742 and 0.745, respectively." (PMID 36560410, 2022). "In this study, serum biochemical indices, histopathology, and expression of TNF-α/NF-κB pathway genes after infection with S. agalactiae were investigated using golden pompano as experimental subjects." (PMID 36139883, 2022). "In the cerebellum, expression of IFNγ and IL12 decreased at days 60 and 120 post-infection, and TNFα remained high." (PMID 35216083, 2022). "Here, we focused on the change in TNF-α and IL-1β message levels in the brain tissue of mice after infection with F. nucleatum." (PMID 35813949, 2022). "The proinflammatory cytokines, TNFα and IL1β are key components of the innate immune response to infection." (PMID 35812870, 2022). "Cytokines, such as IFNs, chemokines, tumor necrosis factor (TNF) and IL, play pivotal roles in the process of anti-infection immune and inflammatory responses." (PMID 35328701, 2022). "The level of TNF-α was also significantly (p < 0.05) reduced upon infection with M. s_Rv1515c as compared to M. s_Vc." (PMID 35813825, 2022). "Given the critical role of pro-inflammatory cytokines in the macrophage response to infection, we compared the levels of TNFα and IL1β in the NT and CMPK2 knockdown (KD) macrophages in response to Mtb infection." (PMID 36451821, 2022). "NF-κB signaling is responsible for the activation of several proinflammatory cytokines, such as (TNF-α), IL-6, and IL-18, which are important for infection control." (PMID 35453567, 2022). "Some inflammatory cytokines, including IL-1β, IL-6, IL-8, and TNF-α, were frequently measured during biomaterial-related infections." (PMID 35203495, 2022).
infection (continued). "This contradicted previous studies that reported experimental infection with P. gingivalis induced TNF and/or IL-1 expression in pregnant animals." (PMID 36042379, 2022). "Infection of P. gingivalis increased the expression of IL-1β (precursor), IL-1β (mature), and TNF-α proteins in MBECs." (PMID 35453424, 2022). "To address this important question, we modified our experimental strategy by treating bacteria-infected mice with TNF-α antibody daily from D6 (disease onset) to D10 (severe infection)." (PMID 35479068, 2022). "Blockade of TNF-α has been shown to reduce nitric oxide production by macrophages during primary infection." (PMID 36145686, 2022). "The overexpression of the TNF-α gene in the THP-1 monocytic cell line against infections produced by the six Aeromonas spp." (PMID 35874671, 2022). "The mRNA levels of multiple pro-inflammatory cytokines, such as interleukin-1β (IL-1β), IL-6, tumor necrosis factor-α (TNF-α), and interferon-β (IFN-β), were up-regulated during the three PRV variants infection." (PMID 35458442, 2022). "Meanwhile, the mRNA levels of IL-6, IP-10, TNF-α, and IL-1-β were increased during reinfection but were lower than those during primary infection." (PMID 35893674, 2022). "Studies have shown that TNF-α promotes inflammation at the site of infection by inducing the production of other proinflammatory cytokines in the vicinity of infection." (PMID 35928151, 2022). "TNF-α is a primary inflammatory factor released in the skin after trauma, injury, or infection and triggers the expression of other pro-inflammatory cytokines including IL-6, IL-8, and IL-1β." (PMID 36432834, 2022). "We further assessed the TNF signaling pathway (hsa04668) in MKN-28 cells affected by ΔhtrA mutant infection using the KEGG enrichment pathway analysis." (PMID 37193047, 2022). "Tumor Necrosis Factor- α (TNF-α) and IL-6 concentrations were significantly higher during the acute phase of infection compared to HD." (PMID 35456119, 2022). "In the recent infection group, 81.2%, 87.5% and 68.7% of the individuals responded to Pep-S, Pep-M and Pep-N, respectively, in terms of the frequency of TNF-α-producing CD4+ T-cells." (PMID 34967260, 2022). "But in cells already infected with Ld, the uptake of miR-122–containing EVs was found to be significantly compromised with concomitant reduction in miR-155 or TNF-α production in the infection context." (PMID 35210329, 2022). "Other pro-inflammatory cytokines such as IL-1β, IL-6, and TNF-α are regulators of host responses to infection and positive mediators of inflammation." (PMID 36320076, 2022). "During injury or infections, tissues rapidly release pro-inflammatory factors, such as interleukin 1 (IL-1) and tumor necrosis factor α (TNF-α)." (PMID 35215890, 2022). "In these macrophages, iNOS is induced by the T helper 1 (Th1) cytokines interferon (IFN), interleukin-1 (IL-1), and tumor necrosis factor-α (TNFα), which are mobilized in the initial phase of the immune response to pathogen infection." (PMID 35323682, 2022). "As a critically important inflammatory marker and drug target in sera, TNFα can be significantly induced after infection or injury via the activation of the immune cells." (PMID 35621957, 2022). "In the heart and pancreas, CVB3/28 infection induced a strong inflammatory cytokines production, such as IL-10, TNF-α, and MCP-1." (PMID 36016091, 2022). "Infection with Toxoplasma gondii induces the secretion of proinflammatory cytokines, including TNF-a." (PMID 36544093, 2022). "NK cells play a vital role in the regulation of the early immune response to infections by producing proinflammatory cytokines (TNF-α, IFN-γ) that further regulate the function of other innate and adaptive immune cells." (PMID 36501067, 2022). "In total, 218 KEGG pathway concentrations were related to infection and other diseases and 73 signaling pathways mostly related to inflammation and immune pathways, such as TNF signaling pathway and MAPK signaling pathway." (PMID 35818408, 2022).